CRP (C-reactive protein)
Diseases named in the same sentence as CRP in open-access papers (continued):
Sharing a sentence is not in itself a finding about the gene and the disease.
appendicitis (continued). "The covariates tested were age, CCI, complicated vs. uncomplicated appendicitis, operative technique, white blood cell count and/or CRP at admission, and insurance status." (PMID 35107591, 2022). "In our study, CRP cut off was higher, however, still able to predict complicated appendicitis with 79.5% accuracy, and a similar positive predictive value and positive likelihood ratio." (PMID 35495380, 2022). "•CRP has the highest specificity for complicated appendicitis and the highest positive likelihood ratio for perforated appendicitis." (PMID 35495380, 2022). "More recently, has been described in the literature a median of C-reactive protein in complicated appendicitis ranging from 97.6 mg/L to 101 mg/L." (PMID 35106154, 2022). "Among these, 1076 had presented for the first time with acute abdominal pain and had CRP levels measured, with 70 (6.5%) having appendicitis (13 had a perforated appendix)." (PMID 35535699, 2022). "Test characteristics of CRP for appendicitis in children with acute abdominal pain at different cut-off levels." (PMID 35535699, 2022). "Another study in the pediatric age group contradicted our findings of CRP being a superior marker of complicated and perforated appendicitis." (PMID 35495380, 2022). "Among the analytical parameters evaluated in our study, C-reactive protein is the only one that proved to be a good predictor of complicated acute appendicitis." (PMID 35106154, 2022). "The objectives of the study were to establish the function of bilirubin as a novel diagnostic tool for predicting complex appendicitis and to compare the impact of other variables such as white blood cell count (WCC), C-reactive protein (CRP), and neutrophil." (PMID 36237793, 2022). "In the multivariate analysis, age, number of daily new cases, vaccination rate, DNI, and CRP were identified as independent relevant factors for complicated appendicitis." (PMID 35433818, 2022). "This study focussed on white blood cell count and CRP as the inflammatory markers, as these have previously been identified as the most useful inflammatory markers of acute appendicitis." (PMID 36051710, 2022). "Using IPD identified a combination of WCC or CRP (WCC >10 000 cell/μL or CRP >10 mg/L) to lead to the least cases of missed appendicitis (n=12)." (PMID 36328382, 2022). "By using our data, both models showed significance for the prediction of complicated appendicitis so we thought the threshold of serum CRP level from the two models is appropriate for the scoring models of the combination of several factors." (PMID 34314464, 2021). "The area under the curve was 0.843, and high serum CRP level was a significant indication factor for complicated appendicitis (p < 0.001)." (PMID 34314464, 2021). "Combined normal WBC and CRP levels are seen in about 2 per 100 patients with confirmed acute appendicitis and can, although rarely, be found in patients with complicated appendicitis." (PMID 33907858, 2021). "Some studies reported sensitivities and specificities of CRP level in predicting pediatric appendicitis, ranging from 0.50–0.95 to 0.25–0.85, respectively." (PMID 34178892, 2021). "Although body temperature, WCC and CRP concentrations in patients with complicated acute appendicitis were higher, the duration of the symptoms was similar in the complicated and uncomplicated appendicitis groups." (PMID 34392384, 2021). "The present study showed that DNI was more accurate than the WBC count, neutrophil percentage, and CRP for predicting perforation in appendicitis patients." (PMID 34011068, 2021). "We compared the serum levels of CRP of the patients between uncomplicated and complicated appendicitis groups." (PMID 34314464, 2021). "DNI% alone, or in combination with other parameters such as leukocyte and CRP, is an effective parameter in predicting acute appendicitis and distinguishing between simple/complicated appendicitis." (PMID 33936912, 2021).
appendicitis (continued). "Accordingly, ROC curve analysis was operated to determine the diagnostic efficacy of CRP, PAS, and urinary 5-HIAA as predictors of the acute appendicitis." (PMID 33898036, 2021). "Since the serum CRP level reaches the maximum level in 48 hours, we consider that elevated CRP can be very useful in the diagnosis of cases with a delayed diagnosis of appendicitis and complicated appendicitis." (PMID 33936912, 2021). "Two scoring models (Atema score and Imaoka score) for the prediction of complicated appendicitis both contained the presence of fluid collection for scoring and also both models recommended combining other factors such as serum level of CRP." (PMID 34314464, 2021). "Some research reported that white blood cell (WBC), C-reactive protein (CRP), and urinalysis appearances can predict pediatric appendicitis." (PMID 34178892, 2021). "CRP levels at first contact were compared to the final diagnosis of appendicitis reported in the specialist reports within six weeks." (PMID 33789755, 2021). "The results showed that CRP level was significantly higher in the complicated appendicitis group compared by uncomplicated appendicitis group (p < 0.001)." (PMID 34314464, 2021). "CRP is a crucial laboratory test and the most widely used predictor for diagnosing complicated acute appendicitis." (PMID 34645500, 2021). "In predicting complicated appendicitis, the area under the curve of the delta neutrophil index and C-reactive protein were 0.671 and 0.709, respectively." (PMID 33936912, 2021). "Age, C-reactive protein, and the delta neutrophil index ​​were statistically significantly higher in the complicated appendicitis group." (PMID 33936912, 2021). "90.7% of all uncomplicated Appendicitis had normal CRP level (< 0.6 mg/dl) whereas only 14% of complicated appendicitis subjects had normal CRP level." (PMID 33509122, 2021). "The predicted existence-rates (positive predictive values) of complicated appendicitis were 52.7% for serum CRP level ≥50mg/L, 74.4% for ≥100mg/L, and 82.6% for ≥150mg/L." (PMID 34314464, 2021). "The DNI% and CRP values ​​were significantly higher in the complicated appendicitis group compared to the simple appendicitis group (p = .002 and .000, respectively)." (PMID 33936912, 2021). "In our cohort, four patients with normal WBC and CRP levels had a final diagnosis of complicated appendicitis, of which one perforated appendicitis." (PMID 33907858, 2021). "We consider that the delta neutrophil index ​​is an effective and reliable parameter in diagnosing acute appendicitis and differentiating simple/complicated appendicitis, especially when combined with the analysis of leukocyte and C-reactive protein." (PMID 33936912, 2021). "Independent factors closely related to the severity of appendicitis included age, weight for age, onset time, admission temperature, leukocyte count, neutrophil ratio, C-reactive protein (CRP), procalcitonin (PCT), and total bilirubin." (PMID 34869120, 2021). "In only 23 of 1303 patients (1.8%) with proven appendicitis, both preoperative white blood cell count and C-reactive protein levels were normal." (PMID 33907858, 2021). "Rest 86% of complicated appendicitis subjects had statistically significant rise of CRP (> 0.6 mg/dl) which was raised only 9.3% of uncomplicated appendicitis cases." (PMID 33509122, 2021). "We aimed to investigate the efficacy of the complete blood count parameters, C-reactive protein, and Lymphocyte-C-reactive Protein Ratio laboratory tests in the diagnosis of acute appendicitis, as well as their relationship with appendix diameter." (PMID 32069909, 2020). "[Acute appendicitis] AND [normal inflammatory markers OR normal C-reactive protein OR normal CRP OR normal white cells counts OR normal WCC]." (PMID 32983436, 2020).
appendicitis (continued). "Nevertheless, the literature admits that the elevation of biological markers such as WBC count, PN count and CRP is often observed in acute appendicitis, but it lacks of specificity, especially when it is isolated." (PMID 32248803, 2020). "Combining routine admission blood markers (WBC, neutrophil count, and CRP) can assist in diagnosing appendicitis in unwell patients with abdominal pain." (PMID 33133811, 2020). "Among preoperative inflammatory biomarkers, CRP value was significantly higher in complicated appendicitis patients than in simple appendicitis patients." (PMID 32180028, 2020). "The conclusion was that the combination of CRP and WCC has greater diagnostic accuracy in acute appendicitis." (PMID 32983436, 2020). "We recommend against basing the diagnosis of acute appendicitis in elderly patients only on elevated leukocytes count and CRP value." (PMID 32156296, 2020). "This is similar to findings published by Andersson who found that a combination of WBC >10 and a CRP >8 gave an accuracy of 0.96 (area under the curve) for diagnosing appendicitis." (PMID 33133811, 2020). "Multiple studies have examined the sensitivity of CRP level alone for the diagnosis of appendicitis in patients selected to undergo appendectomy." (PMID 32070390, 2020). "Eligible patients were defined as those presenting with both normal WCC and CRP with a histologically confirmed acute appendicitis." (PMID 32983436, 2020). "Birchley demonstrates that combining WBC count, neutrophil count, and CRP gives an odds ratio of 18 when trying to identify acute appendicitis - although it should be noted that this is only applicable when all of those tests are abnormal." (PMID 33133811, 2020). "As indicated in many studies, serum WBC and CRP levels increase in patients with acute appendicitis, and the laparoscopic method is recommended." (PMID 33014470, 2020). "The patient with appendicitis was older and had peritonitis, higher preoperative WBC count or CRP level, longer time from diagnosis to surgery, appendicolith, and complicated appendicitis, predicting a prolonged hospital stay." (PMID 33296384, 2020). "Seven patients with histologically confirmed appendicitis had a normal CRP, WBC count and neutrophil count." (PMID 33133811, 2020). "In another study, it was found that CRP supports the clinical diagnosis of acute appendicitis in patients with typical clinical features." (PMID 32069909, 2020). "Our research builds on that premise and demonstrates that while elevated WBC, neutrophil count, and CRP in isolation can be helpful in aiding the clinical diagnosis of acute appendicitis, they are more useful when combined." (PMID 33133811, 2020). "This study also demonstrated that the WBC count and CRP level can be helpful in diagnosing appendicitis." (PMID 33050667, 2020). "A study, which analysed the relationship of the severity of acute appendicitis with PCT and CRP, detected an elevation in both parameters in complicated acute appendicitis cases." (PMID 32399305, 2020). "Although CRP is an indicator of complication appendicitis, the body's inflammatory response to acute appendicitis is a dynamic process." (PMID 32802044, 2020). "CRP help to diagnose equivocal cases of appendicitis, cholecystitis, pancreatitis and pelvic inflammatory disease but faster and more interpretable tests are available." (PMID 33266250, 2020). "For example, the risk of perforation in pediatric appendicitis was reported to correlate with increased white blood cell count (WBC) and C-reactive protein (CRP)." (PMID 31641539, 2019). "For the diagnosis of appendicitis, a selective biomarker signature was developed containing basophils, leukocytes, monocytes, neutrophils, CRP and the appendiceal diameter." (PMID 31553729, 2019).
appendicitis (continued). "In logistic regression analysis, our results showed that elevated white blood cell count (>12000 mm3) with CRP level (>8 mg/dL) and elevated neutrophils percentage (>74%) with CRP (>8 mg/dL) increased the odds of a perforated diagnosis of acute appendicitis." (PMID 31641539, 2019). "There are studies which show that healthy WBC and CRP levels in a patient exclude the possibility of acute appendicitis." (PMID 31183274, 2019). "The diagnostic capacities of the developed biomarker signatures were compared to single widely accepted values for diagnostics of acute appendicitis: CRP, leukocytes, neutrophils and appendiceal diameter." (PMID 31553729, 2019). "There was a statistically significant difference between the acute abdomen and perforated appendicitis in terms of age, FA, CRP, WBC, and sex." (PMID 31547519, 2019). "For the differential diagnosis of complicated versus uncomplicated appendicitis, a selective biomarker signature was developed including basophils, eosinophils, monocytes, thrombocytes, CRP, supplemented by the appendiceal diameter." (PMID 31553729, 2019). "Only nine of the 208 patients whose pathology reports confirmed appendicitis had healthy values for both CRP and WBC." (PMID 31183274, 2019). "Increased levels of CRP have been found in patients with appendicitis, cholecystitis, pancreatitis, and meningitis." (PMID 29706967, 2018). "In this prospective study we analyzed 500 patients with suspected appendicitis, and evaluated the utility of early changes in serum CRP concentrations in the diagnosis of acute appendicitis." (PMID 29793425, 2018). "The C reactive protein (CRP) is one of the most accurate inflammatorymarkers in acute appendicitis (AA)." (PMID 29513800, 2018). "Among the patients with complicated appendicitis, CRP was positive in 69.5% of patients compared to 47% of patients with simple appendicitis." (PMID 29552432, 2018). "In patients suffering possible symptoms of appendicitis, acute appendicitis can be excluded in those with CRP levels lower than 25 mg/L in blood taken 12 h after the onset of symptoms." (PMID 29706967, 2018). "The delta CRP was positive in 73% patients with appendicitis and in 46% patients with normal appendix; the difference was significant (P < 0.001)." (PMID 29793425, 2018). "White blood cell (WBC) counts and C-reactive protein (CRP) levels are commonly used in the assessment of suspected appendicitis, but their sensitivity and specificity vary widely between different studies." (PMID 29552432, 2018). "ROC analysis showed that a cut-off value of serum CRP more than 4.5 mg/L on day 2, or the increase in CRP above 15.0 mg/L on day 3 were good predictors of acute appendicitis in children." (PMID 29793425, 2018). "CRP should be a more valuable predictor for complicated appendicitis than an early simple appendicitis." (PMID 28747992, 2017). "The more recently introduced appendicitis inflammatory response (AIR) score incorporated the C-reactive protein value in its design and was developed and validated on a prospective cohort of patients with suspicion of acute appendicitis." (PMID 28702076, 2017). "Elevated C-reactive protein (CRP) levels are common in acute appendicitis, but studies disagree on its sensitivity and specificity." (PMID 28747992, 2017). "The pooled sensitivity of C-reactive protein for the diagnosis of acute appendicitis was 0.76 (95 % CI 0.75–0.78; I2 = 81.4 %), and its pooled specificity was 0.50 (95 % CI 0.48–0.52; I2 = 94.2 %)." (PMID 27495334, 2017). "Other investigators have sought to develop protein biomarkers for appendicitis in the blood, such as bilirubin, C-reactive protein (CRP), and pro-calcitonin (PCT)." (PMID 27417541, 2016). "In our study in patients with complicated appendicitis when WBC counts were used in combination with CRP, sensitivity and NPV increased to 98.7 and 99.5%, respectively, while specificity regressed to 71.3 percent." (PMID 27274988, 2016).
appendicitis (continued). "Many studies looking at the power of CRP in predicting complications of appendicitis have been published recently showing positive results." (PMID 27330547, 2016). "All patients without any of the three predictive factors (body temperature ≥37.4 °C, CRP level ≥4.7 mg/dl, and fluid surrounding the appendix on CT) had uncomplicated appendicitis." (PMID 27708690, 2016). "As a consequence, CRP level should be routinely evaluated in patients with initial diagnosis of appendicitis." (PMID 27274988, 2016). "In our patient, the diagnosis was established by CT since the patient was considered to have a complicated condition due to the presence of atypical appendicitis, elevated leukocyte level, neutrophil dominance, and increased CRP level." (PMID 27069699, 2016). "In our study, among 32 cases with WBC within normal limits, 24 acute and 8 complicated appendicitis cases were diagnosed, and in 70 cases with normal CRP values 61 acute and 9 complicated appendicitis cases were detected." (PMID 27274988, 2016). "Further studies evaluating INR and CRP in patients undergoing conservative management for appendicitis are required." (PMID 27330547, 2016). "The results of the present study support the use of CRP as a predictor for complicated appendicitis." (PMID 27330547, 2016). "Recently, many novel inflammatory markers have been used to confirm the diagnosis of appendicitis; the most prevalently used laboratory markers for reinforcing the diagnosis are still white blood cell counts and C-reactive protein." (PMID 27274988, 2016). "When evaluating odds ratios (OR) for visualization of the appendix, appendicitis had an OR of 11.8 (95% CI 5.8–24.2) (p < 0.01), and CRP an OR of 1.9 (95% CI 1.2–3.0) (p < 0.01)." (PMID 28044133, 2016). "Multiple logistic regression analyses showed that initial CRP significantly predicted the presence of complicated appendicitis [odds ratio (OR) 1.301, 95% confidence interval (CI) (1.092–1.549), p = 0.003]." (PMID 26859663, 2016). "Area under curve (AUC) for the ability of serum DNI and CRP to predict the presence of acute complicated appendicitis were 0.738 and 0.840, respectively." (PMID 26859663, 2016). "In the stepwise logistic regression analysis formed with risk factors, it was determined that disulphide/native thiol and CRP are independent predictors of perforated appendicitis." (PMID 27642237, 2016). "In many studies, increase in WBC has been reported as the earliest sign of appendiceal inflammation, while increase in CRP levels has been indicated in more advanced stages of appendicitis." (PMID 27274988, 2016). "The value of the C-reactive protein and the percentage of leukocytes segmentedblood count showed a direct relationship with the phase of acute appendicitis." (PMID 26537139, 2015). "Patients were admitted to the hospital for acute abdominal pain, increased neutrophil count and C-reactive protein, and ultrasonographic signs of acute appendicitis." (PMID 25757997, 2015). "In the younger patient group, patients with complicated appendicitis were more likely to be female (P = 0.02), more likely to have appendicolitiasis (P = 0.01), greater appendix diameter (P = 0.02), and higher CRP level (P = 0.03)." (PMID 25587352, 2014). "Patients with complicated appendicitis were more likely to have higher RPS count (P < 0.001), appendicolithiasis (P = 0.002), higher CRP level (P < 0.001), and greater appendix diameter (P < 0.001) than patients with uncomplicated appendicitis." (PMID 25587352, 2014). "CRP level in the acute appendicitis group was significantly higher compared with the control group (P < 0.001)." (PMID 24693387, 2013). "RDW, leukocyte count, and CRP had a sensitivity and specificity of 47% and 67%; 91% and 74%; and 97% and 41%, respectively in acute appendicitis." (PMID 24216220, 2013).